MIR589 (microRNA 589)
Synonyms: hsa-mir-589; MIRN589; mir-589
Gene: MicroRNA gene on chromosome 7 (5,495,819 to 5,495,917, reverse strand). Ensembl gene ENSG00000207973.
Gene Ontology:
Biological process: miRNA-mediated post-transcriptional gene silencing
Cellular component: RISC complex